GTF3C1 (general transcription factor IIIC subunit 1)
Description:
Required for RNA polymerase III-mediated transcription. Component of TFIIIC that initiates transcription complex assembly on tRNA and is required for transcription of 5S rRNA and other stable nuclear and cytoplasmic RNAs. Binds to the box B promoter element.
Synonyms: TFIIIC220; TFIIIC; TFIIICalpha
Tractability: PROTAC: UniProt records ubiquitination sites on it; ubiquitination databases record sites on it; its protein half-life has been measured.
Gene: Protein-coding gene on chromosome 16 (27,459,555 to 27,549,960, reverse strand). Ensembl gene ENSG00000077235.
Subcellular location: Nucleus
Subcellular location (Human Protein Atlas): Nucleoli; Nucleoplasm
Pathways (Reactome):
Gene expression (Transcription): RNA Polymerase III Abortive And Retractive Initiation; RNA Polymerase III Transcription Initiation From Type 1 Promoter; RNA Polymerase III Transcription Initiation From Type 2 Promoter
Gene Ontology:
Molecular function: protein binding; RNA polymerase III general transcription initiation factor activity; DNA binding
Biological process: transcription initiation at RNA polymerase III promoter; 5S class rRNA transcription by RNA polymerase III; rRNA transcription; transcription by RNA polymerase III; tRNA transcription; tRNA transcription by RNA polymerase III
Cellular component: membrane; nucleoplasm; nucleus; transcription factor TFIIIC complex; ribonucleoprotein complex
Genetic constraint (gnomAD): Loss-of-function variants: 39 observed, 143.15 expected, observed/expected ratio (o/e) 0.27, 90% interval 0.21 to 0.36. The upper end of that interval is the gene's LOEUF score, 0.36, which puts it in group 1 of 6, group 1 being the genes least tolerant of losing a copy. Missense variants: 1,662 observed, 2,100.4 expected, observed/expected ratio (o/e) 0.79, 90% interval 0.76 to 0.82. Synonymous variants: 831 observed, 835.26 expected, observed/expected ratio (o/e) 0.99, 90% interval 0.94 to 1.05.
Homologues: Orthologues: chimpanzee GTF3C1 (99% identical), macaque GTF3C1 (92% identical), dog GTF3C1 (82% identical), pig GTF3C1 (81% identical), mouse Gtf3c1 (78% identical), rat Gtf3c1 (78% identical), rabbit GTF3C1 (76% identical), tropical clawed frog gtf3c1 (53% identical), Drosophila melanogaster CG7099 (20% identical), Caenorhabditis elegans tftc-1 (15% identical).
Diseases named in the same sentence as GTF3C1 in open-access papers:
GTF3C1 is named in the same sentence as 21 diseases in open-access papers, as found by Europe PMC text mining. Sharing a sentence is not in itself a finding about the gene and the disease. The quoted sentences say what the papers report.
breast carcinoma (8 papers, 2015 to 2025). "TFIIIC, and in particular its largest subunit GTF3C1, has been shown to acetylate H3K18 in vitro and in vivo upon serum starvation in human T47D luminal breast cancer cells." (PMID 36835038, 2023).
central nervous system cancer (1 paper, 2021). "Among all GTF3 members, GTF3A was particularly highly expressed in CRC compared to normal tissues, whereas GTF3B, GTF3C1, and GTF3C2 had low expression levels in other types of cancers such as brain and central nervous system cancers, esophageal cancer, and leukemia." (PMID 33925358, 2021).
colorectal cancer (1 paper, 2021). A primary or metastatic malignant neoplasm that affects the colon or rectum. "The general transcription factor III (GTF3) family, comprising GTF3A, GTF3B, GTF3C1, and GTFC2, were stated to be linked with the expansion of different types of cancers; however, their messenger (m)RNA expressions and prognostic values in colorectal cancer need to be further investigated." (PMID 33925358, 2021).
injury (1 paper, 2025). Damage inflicted on the body as the direct or indirect result of an external force, with or without disruption of structural continuity. "To assess the effect of the lncRNA GTF3C1 in the repair of diabetic corneal injury, we performed subconjunctival injection of adenovirus-negative control (Ad-NC) and adenovirus containing the GTF3C1 gene (Ad-GTF3C1) in diabetic mice." (PMID 40790772, 2025).
pancreatic tumors (1 paper, 2025). "Targets of GTF3C1 and SYNCRIP, both of which are upregulated in metastatic pancreatic tumors compared to primary tumors, were also significantly increased in expression in high-ColX module gender-specific PAAD cohorts." (PMID 39939916, 2025).
cancer (7 papers, 2010 to 2024). A tumor composed of atypical neoplastic, often pleomorphic cells that invade other tissues. "GTF3C1 is part of the GTF3 family, which is related to the expansion of different types of cancers." (PMID 37627046, 2023).
tumor (7 papers, 2010 to 2025). "Conversely, preferential activation of GTF3C1 in co-culture with transformed epithelial cells may lead to increased ribosome biogenesis and protein synthesis with tumor promoting effects." (PMID 33228208, 2020). "Consistent with the bioinformatic prediction, GTF3C1, NR1H3, NTHL1, SNX, TMEM132A and WIZ expressions were markedly upregulated in the tumor group relative to the normal group." (PMID 41573564, 2025). "In contrast, the expression levels of GTF3B, GTF3C1, and GTF3C2 in CRC were lower in tumor tissue compared to normal tissues." (PMID 33925358, 2021).
GTF3C1 also shares sentences with these, for which no sentence is quoted: melanoma (2 papers); neuroblastoma (2); neurodevelopmental disorder (2); breast ductal carcinoma (1); Cerebellar atrophy (1); cervical cancer (1); Epstein-Barr virus infection (1); esophageal cancer (1); glioblastoma (1); infiltrating ductal carcinoma (1); leukemia (1); mastitis (1); nasopharyngeal carcinoma (1); neurological disorder (1).